RNA5S8 (RNA, 5S ribosomal 8)
Synonyms: RN5S8
Gene: Ribosomal RNA gene on chromosome 1 (228,625,909 to 228,626,027, reverse strand). Ensembl gene ENSG00000200343.
Gene Ontology:
Molecular function: structural constituent of ribosome
Cellular component: ribosome
Homologues: Paralogues in human: RNA5S1 (100% identical), RNA5S10 (100% identical), RNA5S11 (100% identical), RNA5S12 (100% identical), RNA5S13 (100% identical), RNA5S14 (100% identical), RNA5S15 (100% identical), RNA5S16 (100% identical), RNA5S17 (100% identical), RNA5S2 (100% identical), RNA5S3 (100% identical), RNA5S4 (100% identical), and 26 more.